MMP1 (matrix metallopeptidase 1)
Diseases named in the same sentence as MMP1 in open-access papers (continued):
Sharing a sentence is not in itself a finding about the gene and the disease.
COVID-19 (28 papers, 2021 to 2025). A disease caused by infection with severe acute respiratory syndrome coronavirus 2. "Moderate/severe COVID-19 children exhibited significantly elevated baseline levels of MMP-1, 2, 3, 7, 8, 9, 12 and 13 compared to mild COVID-19 children, demonstrating that MMPs are associated with disease severity in COVID-19." (PMID 36544496, 2022). "MMP-1 and -3 may be helpful to differentiate COVID-19 from pandemic influenza A (H1N1) and predict the risk of severe manifestations as well." (PMID 35647937, 2022). "In addition, excessively increased MMP-1 enzymatic activity is highly associated with the severe dysregulation of multiple EC activation markers in COVID-19 patients." (PMID 35741101, 2022). "COVID-19 has also been associated with inflammatory processes involving key mediators such as DPP4 and MMP1, which are known to mediate both tissue remodeling and systemic inflammation." (PMID 40843809, 2025). "COVID-19 is characterized by significantly increased levels of MMP-1 and vascular endothelial growth factor (VEGF)-A, which are directly correlated with the severity of the disease." (PMID 39967675, 2025). "The study identified high levels of MMP-1 proteolytic activity in the peripheral blood of individuals affected by COVID-19, particularly those with severe and critical illness." (PMID 37372128, 2023). "Both levels and enzymatic activity of MMP-1 were upregulated in the peripheral blood of patients with COVID-19, especially in severe/critical patients." (PMID 37372128, 2023). "Alongside the significant elevation of MMP-1 observed in COVID-19 patients, there have been reports indicating that the SARS-CoV-2 spike protein can stimulate the expression of MMP-2 to a lesser extent, as well as MMP-3." (PMID 37372128, 2023). "We observed that COVID-19 patients clustered to express higher levels of MMP-1, -2, -14 and -24, and tissue inhibitors of MMPs (TIMPs) -1 and -2." (PMID 35512020, 2022). "MMP1, IL-8, and caspase-3 were evaluated further in alloSCT patients for their potential to differentiate possible IPA cases and patients suffering from COVID-19-associated pulmonary aspergillosis (CAPA) and appropriate control patients." (PMID 35205926, 2022). "Our results also indicate a possible role for MMP-1 and MMP-3 in lung injury associated with COVID-19, two matrix metalloproteases implicated in tissue damage underlying other lung diseases." (PMID 33995342, 2021). "Interrogating expression of individual markers, we found five notable proinflammatory analytes (Caspase-8, EN-RAGE, IL-18, MCP-3, and MMP-1) that were present at higher concentrations in the supernatants of severe COVID-19 patient monocyte cultures compared with healthy monocyte cultures." (PMID 38578283, 2024). "MMP-1 is unequivocally elevated in patients hospitalized with COVID-19." (PMID 37372128, 2023). "Plasma levels of MMP-1 were elevated in patients hospitalized with severe COVID-19." (PMID 37372128, 2023). "Given that enzymes like DPP4 and MMP1 play critical roles in immune regulation and metabolic processes, their dysregulation in the context of viral infection could be central to the metabolic disturbances observed in COVID-19 patients." (PMID 40843809, 2025). "Besides MMP-9, which has been shown to be associated with a high risk of mortality, others, such as MMP-1, MMP-2, MMP-8, and MMP-13 have also been correlated with disease severity and increased risk of death, especially during the acute phase of COVID-19." (PMID 37372128, 2023). "The matrix metalloproteinases MMP-1 and MMP-3 are implicated in tissue damage underlying other lung diseases (D'Armiento and others 1992; Dahlen and others 1999; Greenlee and others 2007), placing them as potential therapeutic objectives to reduce lung injury in COVID-19." (PMID 35674675, 2022).
COVID-19 (continued). "Therefore, the active small molecules Phaseol, Glycyrol and Glyasperin F in licorice may act on CXCL8, IL2RA, STAT3, and MMP1 to treat COVID-19 by reducing tissue damage and inflammatory response." (PMID 36120307, 2022). "In contrast, the expression levels of tumor necrosis factor-related weak inducer of apoptosis (TWEAK), thymic stromal lymphopoietin (TSLP), and matrix metalloproteinases 1 and 3 (MMP-1 and MMP-3) were specifically upregulated in COVID-19." (PMID 40598558, 2025). "Nonetheless, validation studies are required to demonstrate a link between TWEAK, TLSP, MMP-1, and MMP-3 and severe COVID-19." (PMID 35674675, 2022). "To evaluate MMP1, IL-8, and caspase-3 in CAPA patients, we investigated additional COVID-19 patients developing aspergillosis as a secondary infection." (PMID 35205926, 2022). "Our study showed a consistent upregulation of MMPs (MMP1, MMP7, MMP10, and MMP12) in post-COVID-19 individuals, suggesting ongoing remodeling processes in individuals that experienced mild disease." (PMID 36405747, 2022). "We also observed an increase in macrophages and the transcript expression of MMP-1, -2, -14- and 24, as well as TIMP-1 and -2 in the lungs of human COVID-19 patients." (PMID 35512020, 2022). "The clinical study showed that MMP-1 and vascular endothelial growth factor A (VEGF-A) were significantly elevated in hospitalized COVID-19 patients when compared to mild/moderate cases." (PMID 35741101, 2022). "In large airway tissues, genes related to the mucosal layer (MUC4, MUC5AC, MUC5B) as well as cytokine-mediated signaling pathway genes (CCL20, CXCL1, CXCL6, CXCL6, MMP1) and type I interferon genes (IFIT3, ISG15, STAT1, MX1) were upregulated in COVID-19." (PMID 35233546, 2022). "Conversely, TWEAK, TSLP, MMP-1, and MMP-3 are upregulated only in COVID-19." (PMID 35674675, 2022). "Molecular docking showed that Glycyrol, Phaseol and Glyasperin F in licorice may playe a role in treating COVID-19 by acting on STAT3, IL2RA, MMP1, and CXCL8." (PMID 36120307, 2022). "Therefore, licorice is proposed as an effective candidate for the treatment of COVID-19 through STAT3, IL2RA, MMP1, and CXCL8." (PMID 36120307, 2022). "In this study, Phaseol, Glycyrol and Glyasperin F in licorice may treat COVID-19 to reduce the inflammatory response and promote cell survival by acting on CXCL8, IL2RA, STAT3, and MMP1." (PMID 36120307, 2022). "The remaining post-COVID-19 signature shows good agreement with single-cell RNA sequencing data and contains, among others, proteins related to TGFβ signaling, maintenance of the ECM (TGFβ1, BMP-6, MMP1, MMP7), and TNF-signaling (TNFα, TWEAK)." (PMID 36405747, 2022). "In another study, the comparison between the levels of inflammatory factors among hospitalized COVID-19 patients exhibited a positive correlation between serum levels of VEGFA and MMP1, suggesting that MMP1 has a critical role in tissue remodeling and vascular permeability." (PMID 35893698, 2022). "TWEAK, TSLP, MMP-1, and MMP-3 were elevated in COVID-19 cases." (PMID 33995342, 2021). "Meanwhile, COVID-19 displayed an immune profile distinguished by increased Th1 (IL-12, IFN-γ) and Th2 (IL-4, IL-5, IL-10, IL-13) cytokine levels, along with IL-1β, IL-6, CCL11, VEGF, TWEAK, TSLP, MMP-1, and MMP-3." (PMID 33995342, 2021). "In fact, from the group comparison of COVID-19 vs. non-COVID-19, the authors identified 14 specific inflammatory proteins that can be related to SARS-CoV-2 infection, namely CXCL5, CXCL10, CXCL11, Gal-9, IL-18, IL-18R1, IFNγ, LIF-R, MCP-2, MCP-3, MERTK, MMP-1, PD-L1, and TNF." (PMID 35269564, 2022). "However, high content levels in patients with COVID-19 are not exclusive to MMP-1." (PMID 37372128, 2023). "MMP1, IL-8, and caspase-3 protein levels in 20 patients suffering from CAPA and 45 control COVID-19 patients without Aspergillus infections were analyzed (in total 65 patients, 65 samples)." (PMID 35205926, 2022).
diabetes (26 papers, 2012 to 2025). "Conversely, MMP-1 gene expression raised significantly after treatment with SBECD + OTX + CHR compared to diabetes (p < 0.001)." (PMID 38169923, 2023). "Two weeks after the development of diabetes, i.e., week 9, the expression of the mmp-1 was found to be significantly downregulated in Group-II as compared to Group-I, and no significant change in expression was observed in Group-III." (PMID 36776550, 2022). "Crct1 (cysteine-rich C-terminal protein 1) and Mmp1a (matrix metallopeptidase 1a, interstitial collagenase) expression levels were also modulated by diet only in normal pregnancies, but diabetes had an effect in dams fed the breeder diet." (PMID 22701643, 2012). "However, MMP-1 mRNA expression was notably increased following the treatments relative to the diabetes group (p < 0.001)." (PMID 38169923, 2023). "Thus, an increase in expression of mmp-1 was observed in the diabetes group co-infected with latent tuberculosis, although the increase was non-significant." (PMID 36776550, 2022). "Diabetes wound healing is a dynamic process that overlaps proliferation, inflammation and coagulation, among which FN1 and MMP1 play a key role in wound healing." (PMID 37057206, 2023). "The optimum multivariable prediction model from the 33 analytes remaining after controlling for missing data and 4 clinical co-variates (age, BMI, APRI and diabetes), incorporated MMP7, MMP1, AFP, PDGF-AA, APRI and age (AUROC = 0.928, “ELISA model”)." (PMID 27861569, 2016). "In the present study, the expression of the mmp-1 gene was observed to be increased non-significantly at week 13 in latently infected mice with diabetes in comparison with non-diabetic mice." (PMID 36776550, 2022). "After six weeks of diabetes development, i.e., at week 13, an increase was observed in the expression of mmp-1 in Group-II as compared to Group-I, but the increase was not significant." (PMID 36776550, 2022). "Subgroup analysis indicated that the MMP-1 rs1799750 polymorphism was associated with an increased risk of RCT among smokers, drinkers, age ≥60 years and subjects without diabetes." (PMID 31652448, 2019). "Since we previously found that the expression of MMP‐1 and MMP‐9 are increased subsequent to MAC‐SMC cross talk, we questioned now whether HG (ie diabetes) has an effect on this interaction." (PMID 29992758, 2018). "The associations between MMP-1, MMP-9, MMP-10, and TIMP-1 with cfPWV did not materially change after adjustment for age instead of age and diabetes duration." (PMID 29070037, 2017). "The increased MMP-1, MMP-2, and MMP-9 activities and expression induced by high glucose exposure can elevate matrix degradation thereby accelerating atherogenesis and potentially decreasing plaque stability in diabetes." (PMID 27781209, 2016). "However, some studies report increased MMP activity, particularly MMP-1, MMP-2, and MMP-9, with higher blood glucose levels, which could counteract any protective effect of diabetes against AD." (PMID 39105077, 2024). "However, no significant change was observed in the protein levels of MMP-1 at week 9, and a significant decrease was observed in levels at week 13 in the serum of latently infected mice with diabetes compared to those without diabetes." (PMID 36776550, 2022). "Further, diabetes and hyperglycemic conditions lead to a decrease in levels of MCP-1, increased gene expression of mmp-1, and decreased gene expression of mmp-9, which together may lead to a disruption in the process of granuloma formation and in the activation of latent TB infection." (PMID 36776550, 2022). "Besides, some studies have reported that the expression of MMP-1, -2, and -9 increased in non-injured skin of diabetes patients." (PMID 34777244, 2021). "Furthermore the matrix metalloproteinase 1/tissue inhibitor of metalloproteinase 1 (MMP1/TIMP1) pathway may contribute to the breakdown of the blood brain barrier in conditions such as Alzheimer's disease and diabetes." (PMID 23118852, 2012).
diabetes (continued). "Among the MMPs examined, MMP-1, MMP-2, MMP-3, and MMP-7 were detected in all vitreous samples from patients with PDR and control patients without diabetes." (PMID 24392031, 2013). "Moreover, the significant alteration in levels of MMP1, MMP3, MMP11, CHI3L1 and VEGF-A in non-diabetic fibroblasts between day 3 and day 7 after the wound were all abolished in diabetic M1 fibroblasts, and their expression levels were also significantly lower in diabetes." (PMID 38270651, 2024).
bladder cancer (24 papers, 2006 to 2025). "Several other MMPs are also considered as bladder cancer biomarkers: MMP1, MMP3, MMP7, MMP14, and MMP15." (PMID 41228251, 2025). "The mRNA expression of MMP1/11 in bladder cancer samples was significantly higher than that in normal bladder tissues." (PMID 38256890, 2023). "Cabozantinib has been reported to inhibit MMP-1 expression by blocking the HGF-MET signaling pathway in bladder cancer cells." (PMID 31781483, 2019). "The polymorphisms of MMP-1-1607 1G/2G, MMP-2-1306 C/T, and MMP-9-1562 C/T were reported to be related with bladder cancer susceptibility, but the conclusions remain to be inconsistent." (PMID 24390660, 2014). "Higher expression of MMP-1 has been correlated with progression and poor survival in bladder cancer." (PMID 20649989, 2010). "A recent study shows that overactive Stat3 serves as the signal mediator between EGF and MMP-1 for bladder cancer cell migration, invasion and tumor formation." (PMID 18939995, 2008). "Further experiments indicated that MMP-1 expression was higher in bladder cancer cells than normal adjacent tissue and in particular, higher in muscle-invasive than in non-muscle-invasive bladder cancer and that MMP-1 mRNA and protein levels were inhibited significantly in BIU-87-TFPI-2 cells." (PMID 39153052, 2024). "The results indicate that potentially functional MMP-1-1607 1G/2G and MMP-2-1306 C/T polymorphisms may play an important role in the development of bladder cancer." (PMID 24390660, 2014). "In the current study, a total of five case–control studies with 1,141 cases and 1,069 controls were included in the meta-analysis, and the association between MMP-1-1607 1G/2G, MMP-2-1306 C/T, and MMP-9-1562 C/T polymorphisms and bladder cancer risk was explored." (PMID 24390660, 2014). "Only in the cases of MMP1 and MMP10 do the bladder cancer samples have lower marker concentrations than the control samples." (PMID 41228251, 2025). "The strong responsiveness of MMP1 to EGF relies on STAT3 phosphorylation and its interaction with c-JUN, and with this crucial activation of STAT3, T24 cells exhibit malignant characteristics in bladder cancer." (PMID 38320998, 2024). "ACOX1 can be combined with MMP1, suppressor of cytokine signaling 3 (SOCS3) to diagnose oral squamous cell carcinoma (OSCC), and downregulation in bladder cancer might be due to PDK1 down-regulation, suggesting that it might serve as a potential biomarker and therapeutic target for bladder." (PMID 37724116, 2023).
oral squamous cell carcinoma (24 papers, 1998 to 2025). "Similar to our findings, a previous study involving 96 Chinese patients reported that the presence of MMP-1 homozygous allelic variants in the promoter region of the gene contributed to an increased risk of oral squamous cell carcinoma." (PMID 24278120, 2013). "MMP1, identified as upregulated in cancers such as human oral squamous-cell carcinoma and cervical squamous-cell carcinoma, plays a pivotal role in tumor growth and cell motility." (PMID 40362553, 2025). "To investigate the function of fibroblast-derived MMP1 in tumor progression, we established a mouse model of orthotopic transplantation of oral squamous cell carcinoma." (PMID 38320998, 2024). "Overexpression of common genes associated with tobacco-induced oral squamous cell carcinoma (OSCC), such as MMP1, MMP3, MMP9, YAP1, CYP1A1, and CYP1B1, was also observed." (PMID 36835505, 2023). "Hypoxanthine phosphoribosyl transferase 1 (HPRT1) regulates the production of purines and inosine involved in the cell cycle and can enhance chemoresistance via the MMP1/PI3K/Akt axis in patients with oral squamous cell carcinoma." (PMID 36969232, 2023). "A research about human oral squamous cell carcinoma showed that MMP1 was expressed higher in tumor than normal tissue and its higher expression was positively correlated with a shorter overall survival rate." (PMID 35426219, 2022). "ITGA‐2 and MMP‐1 were significantly overexpressed in tissue samples of oral squamous cell carcinoma in comparison to normal mucosa (P <.01 in all experiments)." (PMID 32437034, 2020). "Oral squamous cell carcinoma tissue samples showed MMP‐1 expression as it follows: five tissue samples (50%) showed strong expression of MMP‐1, two patients moderate (20%), and two patients weak expression (20%) of MMP‐1." (PMID 32437034, 2020). "This study examines the association of single nucleotide polymorphisms in promoter regions of MMP-1 and MMP-3 with susceptibility to oral squamous cell carcinoma (OSCC)." (PMID 17919326, 2007). "Moreover, recent studies have shown that MMP1 is highly expressed in human oral squamous cell carcinoma and cervical squamous cell carcinoma." (PMID 34587931, 2021). "MMP1 and MMP10 are expressed in oral squamous cell carcinoma (OSCC) tissues and are considered prognostic indicators." (PMID 40001606, 2025). "Fixing DSaS on this paper, researchers developed a quantitative method for determining matrix metalloproteinase-1 (MMP1), one of the most promising salivary biomarkers for detecting oral squamous cell carcinoma (OSCC)." (PMID 40332506, 2025). "In addition, high levels of matrix metalloproteinase 1 (MMP1) in oral leukoplakia EVs (OLK-EVs) and oral squamous cell carcinoma EVs (OSCC-EVs) have been reported to be relevant to angiogenesis." (PMID 40078996, 2025). "From the table, MMP1 and MMP10 were highly expressed in oral squamous cell carcinoma." (PMID 36941602, 2023). "So far, no data about the MMP‐1 expression in OSCC tissue samples and smoking are available and we were able to demonstrate an overexpression in oral squamous cell carcinoma in comparison to normal oral mucosa." (PMID 32437034, 2020).